Y_RNA (Y RNA )
Gene: Miscellaneous RNA gene on chromosome 14 (103,725,728 to 103,725,825, reverse strand). Ensembl gene ENSG00000253096.
Homologues: Paralogues in human: Y_RNA (63% identical), Y_RNA (62% identical), Y_RNA (61% identical), Y_RNA (60% identical), RNY3P16 (59% identical), Y_RNA (59% identical), RNY1P11 (58% identical), RNY1P5 (58% identical), RNY3P14 (58% identical), RNY3P3 (58% identical), RNY3P5 (58% identical), Y_RNA (58% identical), and 75 more.